PI4KB (phosphatidylinositol 4-kinase beta)
Description:
Phosphorylates phosphatidylinositol (PI) in the first committed step in the production of the second messenger inositol-1,4,5,-trisphosphate (PIP). May regulate Golgi disintegration/reorganization during mitosis, possibly via its phosphorylation. Involved in Golgi-to-plasma membrane trafficking (By similarity). May play an important role in the inner ear development. (Microbial infection) Plays an essential role in Aichi virus RNA replication. Recruited by ACBD3 at the viral replication sites. (Microbial infection) Required for cellular spike-mediated entry of human coronavirus SARS-CoV.
Synonyms: PI4K-beta; PI4Kbeta; PIK4CB; pi4K92; DFNA87; NPIK; PI4KIII; PI4KIIIBETA
Tractability: Small molecule: a structure with a bound ligand is known; a high-quality ligand is known; it belongs to a druggable protein family. Antibody: UniProt places it where antibodies can reach, with medium confidence. PROTAC: ubiquitination databases record sites on it; its protein half-life has been measured; a small molecule that binds it is known.
Target class: Enzyme; Transferase
Gene: Protein-coding gene on chromosome 1 (151,291,792 to 151,328,394, reverse strand). Ensembl gene ENSG00000143393.
Subcellular location: Endomembrane system; Mitochondrion outer membrane; Rough endoplasmic reticulum membrane; Golgi apparatus; Golgi apparatus membrane; Cytoplasm, perinuclear region
Subcellular location (Human Protein Atlas): Golgi apparatus
Pathways (Reactome):
Metabolism: Synthesis of PIPs at the Golgi membrane
Gene Ontology:
Molecular function: 1-phosphatidylinositol 4-kinase activity; 14-3-3 protein binding; protein binding; kinase activity
Biological process: inner ear development; lysosome organization; phosphatidylinositol phosphate biosynthetic process; phosphatidylinositol biosynthetic process; phosphatidylinositol-mediated signaling; receptor-mediated endocytosis; signal transduction
Cellular component: cytoplasmic side of trans-Golgi network membrane; Golgi apparatus; Golgi membrane; cytoplasm; cytosol; endosome; endomembrane system; mitochondrial outer membrane; perinuclear region of cytoplasm; rough endoplasmic reticulum membrane
Genetic constraint (gnomAD): Loss-of-function variants: 22 observed, 74.61 expected, observed/expected ratio (o/e) 0.29, 90% interval 0.21 to 0.42. The upper end of that interval is the gene's LOEUF score, 0.42, which puts it in group 1 of 6, group 1 being the genes least tolerant of losing a copy. Missense variants: 623 observed, 1,035.3 expected, observed/expected ratio (o/e) 0.6, 90% interval 0.56 to 0.64. Synonymous variants: 371 observed, 413.3 expected, observed/expected ratio (o/e) 0.9, 90% interval 0.82 to 0.98.
Homologues: Orthologues: chimpanzee PI4KB (99% identical), mouse Pi4kb (99% identical), guinea pig PI4KB (98% identical), pig PI4KB (98% identical), dog PI4KB (98% identical), macaque PI4KB (98% identical), rat Pi4kb (98% identical), rabbit PI4KB (97% identical), tropical clawed frog pi4kb (88% identical), zebrafish pi4kb (83% identical), Drosophila melanogaster fwd (45% identical), Caenorhabditis elegans pifk-1 (32% identical). Paralogues in human: PI4KA (32% identical), PIK3C2B (18% identical), PIK3C2A (18% identical), PIK3CD (18% identical), PIK3CG (17% identical), PIK3CA (17% identical), PIK3C2G (16% identical), PIK3CB (16% identical), PIK3C3 (11% identical).